PSAT1 (phosphoserine aminotransferase 1)
Diseases named in the same sentence as PSAT1 in open-access papers (continued):
Sharing a sentence is not in itself a finding about the gene and the disease.
tumor (continued). "Indeed, interfering with PSAT1 in cells expressing p5372P significantly impeded tumor cell metastasis, while displaying no obvious effect on cells expressing p5372R." (PMID 36788227, 2023). "Notably, our results showed that the effect of PSAT1 on PDLSCs proliferative activity was not as strong as previously reported in tumour cells." (PMID 36732787, 2023). "Similarly to PHGDH disruption, we found that PSAT1 knockout did not affect the tumor growth in vivo (right)." (PMID 32138178, 2020). "Of note, IKKε, along with the JAK/STAT pathway, has been reported to regulate a cytokine network promoting cellular proliferation in a subset of triple‐negative breast tumours, and PSAT1 overexpression is also a feature of a small fraction of ER+ tumours along with the JAK‐STAT pathway." (PMID 32783398, 2020). "Moreover, subcutaneous and orthotopic lung implants of Nf1‐mutant LUAD cells in nude mice exhibited decreased tumor growth when mice were administered CB‐839 or AOA, supporting glutaminase and/or Psat1 inhibition as a possible treatment strategy in Nf1‐mutant LUAD tumors." (PMID 31036704, 2019). "Both PHGDH and PSAT1 contribute to serine/ glycine biosynthesis, which plays an important role in supporting nucleotide synthesis in rapidly proliferating cells, and recent publications indicate that high expression of PHGDH in tumor tissue is required for cell growth in epithelial malignancies." (PMID 26499495, 2015). "The PSAT1 expression level in BRCA Luminal, however, has a significant negative correlation with tumor purity, indicating enhanced expression within the tumor microenvironment." (PMID 36105075, 2022). "In addition, PSAT1 and PSPH, which catalyze the final and irreversible step of serine synthesis, promote tumor metastasis independent of their serine synthase activity." (PMID 37187454, 2023).
infection (9 papers, 2016 to 2024). The state of being infected such as from the introduction of a foreign agent such as serum, vaccine, antigenic substance or organism. "The analysis of publicly available expression data revealed that the genes of the PPSB, namely PGDH1, PGDH2 and PSAT1 are strongly upregulated after infection of plants with pathogenic bacteria and fungi." (PMID 34424501, 2021). "Knockdown of ATF4 by lentiviral shRNA infection reduced RNA levels of PSAT1 and SHMT2 in T315I-Bcr-Abl-32D cells." (PMID 38987326, 2024). "In our study, all genes encoding these proteins increased their expression due to infection with ncp strains PHGDH (0.99; 1.82), PSAT-1 (0.64; 1.28), and PSPH (1.09; 2.17), and the increase in PSPH expression was confirmed by the RT-qPCR test." (PMID 35746747, 2022). "Psat1 is similarly altered by infection, with transcripts significantly higher in S. mansoni infected mice on both chow and HFD, although transcript levels of HFD infected mice are lower than those of chow infected." (PMID 30483256, 2018). "The differential gene expression observed at day 15 post-infection demonstrated a consistent pattern of gene up regulation of PHGDH and PSAT1 and down regulation of APOC1, FADS2, FXYD2, KIAA0125, and MMP12 over a period of time in HIV-1 infected PBMC." (PMID 26821323, 2016). "The infection of plants with the gram-negative bacteria Pseudomonas syringae, the oomycetes Phytophthora infestans and Phytophthora parasitica and the necrotrophic ascomycetes Botrytis cinerea and Sclerotinia sclerotiorum elevated the expression of PGDH1, PGDH2 and PSAT1 of around two to seven-fold." (PMID 34424501, 2021).
adenocarcinoma (4 papers, 2008 to 2024). A common cancer characterized by the presence of malignant glandular cells. "Conversely, one sample with adenocarcinoma features showed less CPT1A associated with less SHMT2, MTHFD2, and PSAT1 expression." (PMID 33218188, 2020). "To determine the PSAT1 overexpression effect in human adenocarcinoma cells, we stably transfected PSAT1 in SW480 using the Flp-In System." (PMID 18221502, 2008). "Altogether, our data demonstrate that two mechanisms may explain the in vitro resistance to oxaliplatin of adenocarcinoma cells overexpressing PSAT1." (PMID 18221502, 2008).
neurodegenerative disease (2 papers, 2020 to 2022). A disorder of the central nervous system characterized by gradual and progressive loss of neural tissue and neurologic function. "Of the shared proteins, phosphoserine aminotransferase 1 (PSAT1) and TNC (tenascin-C) were shared between AD and FXTAS, ring finger protein 214 (RNF214) was shared between PD and FXTAS, and only PSAT1 was shared between all three neurodegenerative diseases." (PMID 33585555, 2020).
cardiovascular diseases (1 paper, 2025). "Overall, the promising short-term data and the rigorous roadmap for translational validation we plan to incorporate in our studies indicate a viable path toward clinical application of PSAT1 mRNA therapy for cardiovascular diseases." (PMID 40756345, 2025).
genetic diseases (1 paper, 2023). "However, as is the case for other rare and ultrarare genetic diseases, the small number of PSAT1 variants available to inform classification boundaries limited the types of statistical approaches that could be used in our study." (PMID 37812589, 2023).
PSAT1 also shares sentences with these, for which no sentence is quoted: colon adenocarcinoma (3 papers); brain tumor (2); head and neck cancer (2); metabolic disease (2); acute lymphoblastic leukemia (1); astroglioma (1); atherosclerosis (1); bone cancer (1); bone metastasis (1); breast invasive carcinoma (1); cervical squamous cell carcinoma (1); cholangiocarcinoma (1); Cholecystitis (1); cholelithiasis (1); clear cell ovarian carcinoma (1); clear cell renal carcinoma (1); CNS tumors (1); colitis (1); colorectal tumor (1); cystic fibrosis (1); endocervical adenocarcinoma (1); fibroblastic disorder (1); fungal infection (1); gastroenteritis (1); gastrointestinal stromal tumor (1); Glucose intolerance (1); head and neck squamous cell carcinoma (1); Hemoptysis (1); Huntington disease (1); hyperlipidemia (1).
A further 27 diseases each share a sentence with PSAT1 in 1 paper.